TGFB1 (transforming growth factor beta 1)
Diseases named in the same sentence as TGFB1 in open-access papers (continued):
Sharing a sentence is not in itself a finding about the gene and the disease.
connective tissue disorder (45 papers, 2006 to 2025). A disease involving the connective tissue. "The highest scoring IPA network was “Connective Tissue Disorders, Dermatological Disease and Conditions, Developmental Disorder” (score = 39; 23 focus molecules), with TGFB1 as a major node." (PMID 39684443, 2024).
neurological disorders (43 papers, 2008 to 2026). "In addition, IPA upstream regulator analysis predicted that Allo treatment would activate TGFB1 (Transforming growth factor b1), a key factor in preventing inflammation in neurological disorders." (PMID 38189047, 2023). "In cultured human HSCs, sodium valproate, a broad class I and II HDAC inhibitor also used in the clinic to treat a variety of neurological disorders, demonstrated antifibrotic properties by inhibiting the expression of Col1a1 and TGFβ1 without causing toxic effects." (PMID 31117267, 2019).
myopathies (29 papers, 2010 to 2026). "Elevated levels of both MMPs and TGFβ1 have also been reported a variety of myopathies, including fibrotic forms." (PMID 40535569, 2025). "The myopathy of PAD is characterized by myofiber degeneration in association with extracellular matrix expansion, and increased expression of transforming growth factor-beta 1 (TGF-β1; a pro-fibrotic cytokine)." (PMID 26847457, 2016). "Finally, TGFB1 and TGFB3 were upregulated in GM, with TGFB1 particularly overexpressed compared to other forms of myopathy." (PMID 40568658, 2025). "While some catabolic pathways known to drive alcoholic or HIV-1-associated myopathies were also elevated in this co-morbid model (e.g., TGFβ1), consistent expression patterns were not apparent." (PMID 21846370, 2011). "TGFB1 and TGFB3 were expressed at levels similar to other inflammatory myopathies, while their receptors—particularly those for TGFB2 and TGFB3—were more strongly upregulated in ANCA-negative VM than in other IIM subtypes." (PMID 41441888, 2025). "In this study, we define the specific transcriptomic features of GM, revealing a distinct activation of the IFNγ pathway compared to other myopathies, as well as an increase in multiple proinflammatory cytokines, including IL1B, TNF, and TGFB1." (PMID 40568658, 2025).
retinopathy (29 papers, 2007 to 2025). "In addition, the Tgfβ1/TβRII signaling pathway in microglia effectively decreases microglial activation and exhibits a protective effect on neurons in retinopathy." (PMID 36756614, 2023). "The oxygen‐induced retinopathy model of AMD has increased senescent markers (p16Ink4a, p21Cip1 and SA‐β‐gal) and SASP, including Vegf, Il1β, Il6, Tgfβ1, and Pai1." (PMID 39604117, 2025). "Since TGFβ1 levels were not significantly upregulated in the oxygen-induced retinopathy murine retinal environment in which Myh11-derived MSCs were injected, we can only speculate as to the other factors contributing to this myofibroblast differentiation in the eye." (PMID 32978500, 2020).
hematological malignancies (25 papers, 2007 to 2026). "We comprehensively evaluated expression of TGFB1 and its clinical and biological effects across hematological malignancies." (PMID 37925591, 2023). "The expression and clinical significances of TGFB1 in hematological malignancies were analyzed using Hemap and our In Silico curated datasets." (PMID 37925591, 2023). "Our results suggest that TGFB1 is broadly dysregulated in hematological malignancies." (PMID 37925591, 2023). "We therefore analyzed the correlations between TGFB1 expression and TME in hematological malignancies." (PMID 37925591, 2023). "As TGF-β signaling has been reported to be involved in the TME18,19, we continued to explore the correlations between TGFB1 expression and 29 TME signature scores across hematological malignancies." (PMID 37925591, 2023).
infectious disease (25 papers, 2008 to 2026). A disorder directly resulting from the presence and activity of a microbial, viral, or parasitic agent in humans. "Recently, we showed in infectious disease research that T. cruzi dysregulates the expression profile of host piRNAs computationally predicted to target profibrotic molecules including TGFB1, FOS, and NFATC2 in primary human cardiac myocytes." (PMID 36936778, 2023). "Increased TGFβ1 levels in the breast milk of mothers have been observed in those with greater exposure to infectious diseases in childhood." (PMID 32545413, 2020). "Substantiated grounds for IgA-specific effector function via TGFβ1-mediated class-switch would be a new factor to consider for infectious diseases." (PMID 29255469, 2017). "Given that active TGFβ1 contributes to the pathology of many infectious diseases, inhibiting these processes may explain some of the benefits associated with the ingestion of this species." (PMID 33833368, 2021).
respiratory diseases (21 papers, 2011 to 2025). "TGFβ1 is the most recognized isoform involved in respiratory diseases, which is important to the pro-fibrotic switch, matrix production, suppression of lung epithelial cells’ proliferation, and is enhanced during pulmonary inflammation progress." (PMID 32554855, 2020).
benign tumors (16 papers, 2011 to 2025). "The role of TGFβ1 overexpression in these benign tumors remains unclear." (PMID 21975049, 2011).
musculoskeletal disorders (7 papers, 2013 to 2025). "This is of interest because tissues collected from humans with upper extremity work-related musculoskeletal disorders show the presence of fibrosis and its mediators, including IL-6 and TGFB1." (PMID 24015193, 2013). "However, neither TGFB1 nor CTGF have been examined in serum in association with work-related musculoskeletal disorders." (PMID 24015193, 2013). "Serum TNF-α, IL-6, TGFB1, CTGF and MMP2 may serve as serum biomarkers of work-related musculoskeletal disorders, although further studies in humans are needed." (PMID 24015193, 2013).
head and neck tumors (5 papers, 2008 to 2022). "So far, there have been no reports on TGFB1 expression in other prone regions of head and neck tumors." (PMID 31485443, 2019).
central nervous system disease (4 papers, 2017 to 2025). "It has been reported that any central nervous system disease characterized by upregulation of AQP4 on astrocytes may also involve the AQP4/TGFB1 pathway." (PMID 38383423, 2024).
blood cancers (2 papers, 2023 to 2025). "TGFB1 expression were broadly dysregulated in blood cancers and generally associated with adverse prognosis." (PMID 37925591, 2023). "We next investigated genetic alterations (including mutations, amplifications, and deletions) frequencies of TGFB1 across blood cancers." (PMID 37925591, 2023). "We found that TGFB1 expression were broadly dysregulated in blood cancers and generally associated with adverse prognosis." (PMID 37925591, 2023). "We also performed Spearman correlation analysis to uncover the associations between TGFB1 expression and immunomodulatory genes across blood cancers." (PMID 37925591, 2023). "Additionally, TGFB1 expression were associated with distinct TME properties among different blood cancer types." (PMID 37925591, 2023). "TGFB1 expression were associated with distinct TME properties among different blood cancer types." (PMID 37925591, 2023). "In summary, these results suggest that TGFB1 was broadly dysregulated and significantly improved outcome predictions in blood cancers." (PMID 37925591, 2023). "We then examined the correlation between TGFB1 levels and the degree of immune cell infiltration in diverse blood cancers using both CIBERSORT and MCP-counter algorithms." (PMID 37925591, 2023). "In this study, we comprehensively evaluated the expression of TGFB1 (coding gene of TGFβ) and its clinical and biological effects across multiple blood cancer types." (PMID 37925591, 2023). "To further dissect the overall effects of TGFB1 in blood cancers, we investigated the prognostic values of dysregulated TGFB1 expression in three major blood cancer types (AML, DLBCL, and MM)." (PMID 37925591, 2023). "To explore the biological processes associated with TGFB1 expression in blood cancers, we performed differential expression analysis between the top 30% TGFB1 expression subgroup and bottom 30% TGFB1 expression subgroup in each blood cancer type." (PMID 37925591, 2023). "Functional and mechanistic studies are needed to further understand the role of TGFβ1 signaling in blood cancers." (PMID 37925591, 2023). "We next sought to examine the prognostic significances of dysregulated TGFB1 expression in three major blood cancer types (AML, DLBCL, and MM)." (PMID 37925591, 2023). "TGFB1 expression was positively correlated with immune score in most blood cancer types, the most prominent ones being MDS and CML." (PMID 37925591, 2023). "Furthermore, we investigated TGFB1 expression at single-cell resolution in several blood cancer types." (PMID 37925591, 2023). "In summary, we performed the first comprehensive analysis of TGFB1 across blood cancers." (PMID 37925591, 2023). "We first predicted ICB responses in datasets covering five blood cancer types using TIDE and found that predicted responders generally have significantly higher TGFB1 expression than non-responders, especially in AML." (PMID 37925591, 2023).
TGFB1 also shares sentences with these, for which no sentence is quoted: scleroderma (105 papers); head and neck squamous cell carcinoma (66); multiple sclerosis (64); influenza (58); schistosomiasis (57); Loeys-Dietz syndrome (52); tuberculosis (48); Glomerular sclerosis (44); glomerulonephritis (42); ulcerative colitis (41); chronic myeloid leukemia (40); Parkinson disease (39); hereditary hemorrhagic telangiectasia (38); liver (36); hypertrophic cardiomyopathy (34); multiple myeloma (34); clear cell renal cell carcinoma (30); airway hyperresponsiveness (29); amyotrophic lateral sclerosis (29); basal cell carcinoma (27); medulloblastoma (27); acute respiratory distress syndrome (26); graft versus host disease (25); leishmaniasis (25); chronic hepatitis C (24); acne (23); acute myocardial infarction (23); kidney injury (23); myocarditis (23); non-alcoholic fatty liver disease (23).
A further 1,149 diseases each share a sentence with TGFB1 in 23 papers or fewer.